MKI67 (marker of proliferation Ki-67)
Diseases named in the same sentence as MKI67 in open-access papers (continued):
Sharing a sentence is not in itself a finding about the gene and the disease.
tumor (continued). "Moreover PtpA, a significant effector protein that can enter the nucleus of the host cell and control cell migration and proliferation to encourage tumor growth, seems to support MKI67-mediated tumor cell invasion, migration, and proliferation during M. tuberculosis infection." (PMID 36674038, 2023). "Through establishing patient-derived cancer organoids, we found that stem cell-like cells (SOX9+ and MKI67+) may be the main component of tumor epithelial cells in vivo and that these cells can be self-renewal and further differentiate into other mature cell types." (PMID 35974387, 2022). "To investigate the subtypes of monocytes and macrophages that are associated with tumor-related responses, we identified monocytes and macrophages with high expression of cell cycle markers MKI67 and TOP2A, indicating a cluster of proliferating myeloid cells that we termed MKI67+ myeloid cells." (PMID 35013146, 2022). "Finally, MKI67 expression is commonly used as a marker for tumor cell proliferation and growth." (PMID 36005145, 2022). "Moreover, Mki67 plays an important role in tumor microenvironment and congenital immunity." (PMID 36605216, 2022). "Consistent with the observed growth inhibition, MKI67 expression was decreased and GO terms related to cell cycle, DNA repair, mitosis, and progression through G2/M phase were decreased similar to what is observed in other tumor types subjected to chemotherapy." (PMID 33616307, 2021). "Interestingly, according to our previous findings, MKI67 is a potential host gene regulated by Mtb PtpA, a key effector protein that can enter into the host cell nucleus and regulate cell proliferation and migration to promote tumor development." (PMID 33097805, 2020). "Moreover, DDX39 could serve as a prognostic biomarker for ER-positive BC, despite the clinical factors of age, tumor stage, lymph node involvement, and MKI67 status." (PMID 32194796, 2020). "To further validate the clinical utility of the model, we constructed a decision curve analysis (DCA) to compare the prognostic performance of the MRPL family model with that of other established tumor biomarkers, including AFP, MKI67, and KRT19." (PMID 41399509, 2025). "Mapping tumor subpopulations onto this trajectory revealed that C0 NAP1L1+ TCs and C2 MKI67+ TCs generally occupied the early pseudotime segment, C3 ITLN1+ TCs were situated in the intermediate region, and C1 CA2+ TCs were primarily found in the late segment." (PMID 40842994, 2025). "For instance, higher mRNA expression levels of MKI67, ERBB2, and ESR1 have been positively correlated with higher tumor stages and grades, suggesting their potential utility in clinical practice." (PMID 40948378, 2025). "Within this network, we found the well-known marker of proliferation ki-67 (MKI67), often used for quantifying the growth rate of tumor cells." (PMID 39858101, 2025). "Among these, clusters 0, 1, 2, 3, and 7 are tumor cells that highly express MLANA, MITF, SOX10, and MKI67." (PMID 40356756, 2025). "IHC staining of tumor tissues acquired on the day of sacrifice showed decreased MCM2, MCM5, BrdU and MKI67 levels in TRIM21 knockdown groups, contrasting with elevated TCF3 levels." (PMID 40998798, 2025). "At the same time, proliferative markers such as MKI67, TOP2A, PRC1 and RRM2 underscore the importance of cell-cycle dynamics not only in tumor growth but also potentially within rapidly expanding immune subsets that contribute to treatment efficacy." (PMID 40745034, 2025). "Proteomic profiling further revealed its impact on multiple oncogenic and tumor-suppressive proteins, with notable upregulation of SERPINB2, KIT, and NOTCH1, alongside downregulation of COX2, DNMT1, MAPK1, AKT1, MKI67, EP300, and SMC1A." (PMID 41321870, 2025).
tumor (continued). "C1GALT1 was upregulated in several GI and GU cancers, correlating with poor survival and elevated expression of proliferation markers like MKI67, PCNA, and MCM2–7, suggesting a role in tumor growth." (PMID 40548474, 2025). "Then, to investigate the functional impact of the MKI67 gene, we used the GEPIA2 database to extract the top 100 genes with similar expression patterns to MKI67 in all tumor types." (PMID 40070823, 2025). "The correlation between MKI67 expression and survival outcome, clinical features, MSI, TMB, and tumor-infiltrating immune cells by TCGA database, xCell, and TIMER algorithms." (PMID 40070823, 2025). "When specificially examining the tumor samples alone, we found that the cycling HepT population expressed high levels of EZH2, SUZ12, and EED, along with cell cycle regulators MKI67, AURKB, ASPM, TOP2A, and HELLS." (PMID 40766612, 2025). "Regarding tumor stages, SAMD12+ cells were predominantly expressed in stage II tumors, VIM in stage Ib, and both MKI67 and RPLP1 exhibited higher expression levels in stage IV, indicating their roles in advanced tumor progression." (PMID 40666516, 2025). "The expression levels of G6PD, HMGA1, MKI67, RACGAP1, and RFC4, were significantly higher in tumor samples with (p < 0.05)." (PMID 40421085, 2025). "Cells in both tumor models retained proliferative and immature characteristics, as evidenced by c-MYC overexpression and increased MKI67 expression, and decreased expression of MAP2 and GFAP compared to their respective controls." (PMID 40917877, 2025). "Ki‐67 (MKI67) is a protein that is commonly used as a marker to measure the proliferation rate of cells and determine the grade of certain tumours, detected through IHC staining." (PMID 38332687, 2024). "NUTF2 expression was found to be highly correlated with MKI67 and PCNA in 27 tumor types including ACC, BLCA, and BRCA (P < 0.05)." (PMID 38402311, 2024). "HMGB2 in POSTN+ fibroblasts is predicted to bind to PLD2, LRP5, MYLK, and CD44 on tumor cells, regulating downstream genes, including BIRC5, CCNA2, CCNB1, CCNB2, CDC20, and MKI67, which are related to the cell cycle." (PMID 38519500, 2024). "Six tumor-infiltrating CD4+ T-cell clusters (CD4+_FOXP3, CD4+_CCR7, CD4+_LMNA, CD4+_ISG15, CD4+_CXCL13 and CD4+_MKI67) were identified after data filtering, integration, unsupervised clustering and annotation." (PMID 38383773, 2024). "The study also found that the expression level of HMGCS1, HMGCR, SQLE, and NSDHL progressively increased with tumor grade and correlated positively with the expression of MKI67, the gene coding for the proliferation marker Ki67." (PMID 38254664, 2024). "We found that similar with cell proliferation indicator - MKI67, the expression of NDC80 complex components was higher in tumor tissues than in normal tissues in the majority of cancer types." (PMID 39513104, 2024). "The frequencies of the tumor-reactive CD8+_CXCL13 and CD8+_KI67 populations were significantly positively correlated with the frequency of the IFN-producing CD4+_MKI67 population, supporting the concept of a tumor antigen-driven “help” scenario in the TME." (PMID 38383773, 2024). "Protein-coding genes with increased expression across all tumor types included E2F7, ETS1, EZH2, ID3/4, MKI67, PIK3R3, and TOP2A." (PMID 36865335, 2023). "Meanwhile, we observed highly active lactate dehydrogenase in tumor cells, ACKR1+ endothelial cells, MKI67+ macrophages, CD8+ T cells, and vSMC cells." (PMID 37795453, 2023). "Decreased levels of P2RX7-V3 in vivo reduced the expression of Ki-67/MKI67 and VIM and increased CDH1 levels, repressing tumor growth and progression." (PMID 36765733, 2023). "One cluster (C2 Tumor cells) expressed stem-related genes (SOX4 and CD164); the other (C3-Tumor cells) expressed proliferative genes (MKI67 and MCM2)." (PMID 36788228, 2023).
tumor (continued). "Among genes with the highest differential expression between p63pos and p63neg ACC we shortlisted the proliferation marker MKI67 and the cyclin dependent kinase CDK19, both highly upregulated in p63neg tumor (FC > 1.2, FDR < 0.05, p < 0.001)." (PMID 36720951, 2023). "The lactate dehydrogenase and L-lactate dehydrogenase activities of tumor cells, CD8+ T cells, vSMC cells, and MKI67+ macrophages were also higher than other cell types." (PMID 37795453, 2023). "The expression of CDK1, MKI67, TOP2A, and CEP55 was significantly higher in tumor tissue than in normal tissue." (PMID 38134110, 2023). "For tumor-derived organoids cultured for 2 weeks, majority of the cells expressed SOX9/MKI67 (SOX9+ 41.6%, MKI67+ 77.5%, SOX9+MKI67+ 37.7%), but after long-term culture (2 months), less cells expressed SOX9 or MKI67." (PMID 35974387, 2022). "Next, we confirmed the positive linear correlations between the mRNA expression of MKI67 vs. CCNA2, CCNB1, CCNB2, and CCNE2, suggesting their role in tumor progression." (PMID 36151566, 2022). "Of note, MKI67 monocytes and APOE macrophages were mainly derived from tumor, while ADAP2 and MARCO macrophages were mainly from ascites." (PMID 36248860, 2022). "The dot plots showed the proportion of cells expressing tumor stemness-related gene markers (CD44 and MKI67) and key DEeRNAs (PHLDA1 and RASD1) and their scaled relative expression level in 12 cell clusters." (PMID 36092920, 2022). "The expression of MAP2, DYNC1H1, and MKI67 was obviously higher expressed in tumor tissues, while CPS1 and PTPRB were downregulated in tumor tissues compared with normal tissues in TCGA dataset." (PMID 35311113, 2022). "Tumor cells can be divided into 4 different subtypes, including basaloid cells (KRT5, KRT14), myoepithelial cells (ACTA2, MYL), cycling cells (MKI67, TOP2A) and duct-like cells (KRT7, KRT19)." (PMID 35860547, 2022). "These were based on tumor hormonal status, human epidermal growth factor receptor 2 (HER2) status, and proliferation marker protein Ki-67 (MKI67) status." (PMID 36675729, 2022). "The expression of marker genes of C6 cluster cells, including a total of 276 genes such as TOP2A, MKI67, and TK1, was higher in tumor tissues than in normal tissues from TCGA database." (PMID 36046337, 2022). "To explore the relationship between KSR2 and tumor cell proliferation, we examined co-expression of KSR2 and the proliferating cell nuclear antigen (PCNA), human Ki67 (MKI67) protein, and histone deacetylase 1 (HDAC1)." (PMID 35468812, 2022). "Quantitative real-time PCR (qRT-PCR) exhibited that expression of CPS1 and PTPRB was downregulated in tumor tissues compared with paracancerous tissues, while MAP2, DYNC1H1, and MKI67 were overexpressed in tumor tissues." (PMID 35311113, 2022). "The expression of MKI67, MYBL2 and CCNB1 was significantly correlated with miR-200c-3p expression, both in pre- and post-NCT tumor samples." (PMID 35625994, 2022). "The ‘marker of proliferation Ki-67’ (MKI67) and ‘proliferating cell nuclear antigen’ (PCNA) are clinically important indicators commonly used to assess tumor cell proliferation, as well as the degree of malignancy and prognosis." (PMID 36010686, 2022). "Genes such as TOP2A and MKI67 were found in MP6, indicating that this MP is related to the proliferation of tumor cells." (PMID 36423636, 2022). "The six genes of the signature belonged to different functional immune-related groups: antigen presentation (HLA-DPA1 and CD1C), innate immune response (TLR7), type II interferon signaling (IFNB1), tumor marker (MMP2), and proliferation marker (MKI67)." (PMID 34209514, 2021). "We further demonstrate the divergent cell transcriptional states for tumor-infiltrating CD8+ T cells and identify a MKI67 + proliferative subpopulation being a potential culprit for the progression of ccRCC." (PMID 33504936, 2021).
tumor (continued). "In multivariable analyses that included STRAT4 mRNA measurements, tumor size, nodal status, PGR, ERBB2, and MKi67 were independent prognostic factors for time to DR." (PMID 34371382, 2021). "The six genes belonged to different functional groups: antigen presentation (HLA-DPA1 and CD1C), innate immune response (TLR7), type II interferon signaling (IFNB1), tumor marker (MMP2), and proliferation marker (MKI67)." (PMID 34209514, 2021). "Similar to previous studies, SPP1, MTHFD2, TRIP13, MKI67, MMP9, and KLF4 were some of the most clinically valuable tumor markers, especially in CC and EC." (PMID 34834529, 2021). "In comparison to tumor cells from the PT, in CTCs the expression levels of PCNA and MKI67 was reduced 495.5-fold (p-value 0.0008, two-tailed t-test) and 81.9-fold (p-value 0.0054, two-tailed t-test), respectively." (PMID 34885114, 2021). "The tumor markers CDKN2A and KRT7 were the most upregulated genes with fold changes 10.7 and 4.8, respectively, while markers for proliferation (MELK, CDK1, MKI67, CCNB2, BUB1, FOXM1, CDKN3) had fold changes spanning from 2.0–2.7." (PMID 35008799, 2021). "The marker of proliferation Ki-67 labeling index was ∼1%, and the fraction of MGMT immunopositive tumor cells was ∼1%." (PMID 33031279, 2020). "We identified five classes of tumor cells (C8, C9, C10, C18, C20), which expressed the tumor cell marker genes EPCAM, CEACAM6, or MKI67." (PMID 32580738, 2020). "The marker of proliferation Ki-67 labeling index was ∼2%, and the fraction of MGMT immunopositive tumor cells was ∼60%." (PMID 33031279, 2020). "The marker of proliferation, Ki-67 (MKI67), functions to mark tumor cell proliferation, including in the prostate, and has a close relation to the epithelial-mesenchymal transition (EMT)." (PMID 32266115, 2020). "Here, similar to HSD17B4, ACAA1 was also found to be down-regulated and negatively correlated with MKI67 expression in NSCLC, indicating its anti-tumor potential." (PMID 32265992, 2020). "We also demonstrate that MKI67, an over-expressed gene shared by TB and LUAD, is a key mediator in Mtb-promoted tumor cell proliferation, migration, and invasion." (PMID 33097805, 2020). "CCND1 gene expression was highest in luminal A/B and lowest in basal-like tumours, while the opposite was true for CDK4/6 and the proliferation marker gene MKI67." (PMID 30819233, 2019). "Other candidate evofosfamide sensitivity genes—MKI67, POR, and SLFN11—did not strongly influence evofosfamide sensitivity in univariate analyses, although a weak significant relationship with MKI67 was observed, while SLFN11 expression was lost in PDX tumours." (PMID 31337055, 2019). "As MKI67 and MYC are two famous driver oncogenes in carcinogenesis and tumor progression, the relationships between the expression levels of EPB41L4A-AS2, MKI67 and MYC were next explored." (PMID 30764831, 2019). "Here we report that an enhancer, located between the promoters of marker of proliferation Ki67 (MKI67) and O6-methylguanine-DNA-methyltransferase (MGMT) genes, is activated in TMZ-resistant patient-derived xenograft (PDX) lines and recurrent tumor samples." (PMID 30054476, 2018). "Ki67, also known as MKI67, is present in actively proliferating cells in the G1, S, and G2 phases, and is a proliferation-related nuclear marker of tumor cells." (PMID 28834915, 2017). "We tested possible expression changes of five genes (TACSTD, MMP7, ALDH1A3, MKI67, GLUT1) in tumors 48 h and 14 days after mTHPC and Lipidot mediated PDT compared to untreated tumor controls." (PMID 27716314, 2016). "As expected, we found that gene expression patterns are different in PC tumor samples compared to normal, undiseased peritoneum with a number of genes differentially regulated: BAG1, CCNB1, CD44, CLDN4 and 6, MMP2, MKI67, MUC1, MYBL2, and SERPINB3." (PMID 27542596, 2016).
tumor (continued). "In these studies, increased DKC1 expression was related to markers of tumour proliferation, like high TERC, MKI67 and MYC levels." (PMID 26366868, 2015). "We identified six signature LRGs (ALB, G6PD, HMGA1, MKI67, RACGAP1, and RFC4) possess prognostic potential, correlation with immune infiltration, and lactylation-related pathways, providing novel insights into tumor microenvironment (TME) of HCC." (PMID 40421085, 2025). "Additionally, we observed that the cell proliferation markers MKI67 and TOP2A were highly expressed in spatial cluster C5, which was exclusively located in the tumor region." (PMID 39950944, 2025). "Peptide‐mediated inhibition of the PLXDC2‐cortactin binding led to a reduction in the mRNA levels of the tumor‐related genes MYC (p < 0.05) and POU5C1, and the proliferation‐related gene MKI67 (p < 0.05), while the mRNA levels of PLXDC2 and cortactin remained unchanged." (PMID 41365610, 2025). "The HE staining results confirmed the difference in tumor growth among the groups, while staining of CANX, MAP1LC3B, MKI67, and cleaved Caspase 3 confirmed that ND could enhance chemotherapy sensitivity in vivo by reducing the expression of CANX." (PMID 39990231, 2025). "Module5 (Cell cycle) was characterized by expression of Cell cycle-related genes such as MKI67 and CDKN3 and enrichment of cell cycle, E2F targets and G2M checkpoint pathways, which was considered to be the inception of tumor development." (PMID 40406120, 2025). "Hillock cells, mesenchymal stem cells, and MKI67+ epithelial cells were found in organoid samples but not tumor tissues." (PMID 40943497, 2025). "We classified a total of 7,759 tumor cells into separate subpopulations based on their DEGs and designated each cluster according to its most prominently expressed marker gene: C0 NAP1L1+ TCs, C1 CA2+ TCs, C2 MKI67+ TCs, and C3 ITLN1+ TCs." (PMID 40842994, 2025). "Furthermore, the proportion of RMC tumor cells expressing the myeloid lineage marker S100A9 and the cell proliferation marker MKI67 was significantly higher following ICT treatment." (PMID 41290625, 2025). "To ascertain whether the C2 MKI67+ TCs subpopulation is a possible driver of CRC progression, we conducted enrichment analysis among tumor cell subpopulations." (PMID 40842994, 2025). "This was also accompanied by the upregulation of proliferation marker MKI67, costimulatory genes (CD28, TNFRSF9 (4-1BB), and tumor-reactivity markers (e.g., ENTPD1/CD39, ITGAE/CD103) suggestive of an anti-tumor response in face of rising tumor levels." (PMID 37919606, 2024). "In addition, MKI67, AFP, and ALB level, as well as the immune score, the stromal score, and the tumor purity (estimate score), also showed the similar results to those in TCGA-HCC dataset." (PMID 38374122, 2024). "MET was enriched in proliferating tumor cells featuring high levels of markers of cell cycle progression such as cyclins b1 and b2 (CCNB1, CCNB2), proliferating-cell nuclear antigen (PCNA) and Ki67 (MKI67) and likely define yet another subset of MBM." (PMID 38386085, 2024). "Three scRNA-seq datasets GSE125449, GSE140228 and GSE166635 downloaded from the TISCH2 database were analyzed, and we found that CBX2 was primarily expressed in cancerous tumor cells while CEP55 was primarily expressed in T cells that were proliferating (T prolif), whose marker gene MKI67." (PMID 37980163, 2023). "Cluster 5 ductal cells (MKI67+) were almost exclusively present in tumor tissues but not in NT control, suggesting that these are tumor cells of high proliferative capabilities." (PMID 37612267, 2023). "Across the six ductal cell subclusters, we observed an opposite trend of gene expression between proliferating markers (e.g., MKI67) and malignant metastatic markers (e.g., CEACAM5/6 and KLK7), suggestive of orchestrated differentiation of tumor cells during metastasis." (PMID 37612267, 2023).